TUBB4B (tubulin beta 4B class IVb)
Description:
Tubulin is the major constituent of microtubules, a cylinder consisting of laterally associated linear protofilaments composed of alpha- and beta-tubulin heterodimers. Microtubules grow by the addition of GTP-tubulin dimers to the microtubule end, where a stabilizing cap forms. Below the cap, tubulin dimers are in GDP-bound state, owing to GTPase activity of alpha-tubulin.
Synonyms: TUBB2C; Beta2; LCAEOD; TUBB2
Tractability: Small molecule: an approved drug acts on it; a structure with a bound ligand is known; a high-quality ligand is known; it belongs to a druggable protein family. Antibody: its Gene Ontology location is reachable by antibodies, with high confidence. PROTAC: ubiquitination databases record sites on it; its protein half-life has been measured; a small molecule that binds it is known. Other modalities: an approved drug acts on it.
Target class: Structural protein
Gene: Protein-coding gene on chromosome 9 (137,241,287 to 137,243,707, forward strand). Ensembl gene ENSG00000188229.
Subcellular location: Cytoplasm, cytoskeleton; Cytoplasm, cytoskeleton, flagellum axoneme
Subcellular location (Human Protein Atlas): Microtubules; Basal body; Cytokinetic bridge; End piece; Flagellar centriole; Mitotic spindle; Primary cilium; Primary cilium tip; Principal piece
Pathways (Reactome):
Cell Cycle: AURKA Activation by TPX2; EML4 and NUDC in mitotic spindle formation; Loss of Nlp from mitotic centrosomes; Loss of proteins required for interphase microtubule organization from the centrosome; Mitotic Prometaphase; Recruitment of NuMA to mitotic centrosomes; Recruitment of mitotic centrosome proteins and complexes; Regulation of PLK1 Activity at G2/M Transition; Resolution of Sister Chromatid Cohesion; Sealing of the nuclear envelope (NE) by ESCRT-III; Separation of Sister Chromatids; The role of GTSE1 in G2/M progression after G2 checkpoint
Vesicle-mediated transport: COPI-dependent Golgi-to-ER retrograde traffic; COPI-independent Golgi-to-ER retrograde traffic; COPI-mediated anterograde transport; Gap junction assembly; Microtubule-dependent trafficking of connexons from Golgi to the plasma membrane; Translocation of SLC2A4 (GLUT4) to the plasma membrane
Metabolism of proteins: Carboxyterminal post-translational modifications of tubulin; Formation of tubulin folding intermediates by CCT/TriC; Post-chaperonin tubulin folding pathway; Prefoldin mediated transfer of substrate to CCT/TriC
Immune System: MHC class II antigen presentation; Neutrophil degranulation; PKR-mediated signaling
Organelle biogenesis and maintenance: Anchoring of the basal body to the plasma membrane; Cargo trafficking to the periciliary membrane; Intraflagellar transport
Signal Transduction: Hedgehog 'off' state; RHO GTPases Activate Formins; RHO GTPases activate IQGAPs
Neuronal System: Activation of AMPK downstream of NMDARs; Assembly and cell surface presentation of NMDA receptors
Autophagy: Aggrephagy
Cellular responses to stimuli: HSP90 chaperone cycle for steroid hormone receptors (SHR) in the presence of ligand
Developmental Biology: Recycling pathway of L1
Disease: HCMV Early Events
Hemostasis: Kinesins
Gene Ontology:
Molecular function: double-stranded RNA binding; protein binding; GTP binding; MHC class I protein binding; structural constituent of cytoskeleton; GTPase activity
Biological process: mitotic cell cycle; natural killer cell mediated cytotoxicity; cytoskeleton organization; flagellated sperm motility; microtubule-based process
Cellular component: axonemal microtubule; extracellular exosome; extracellular vesicle; microtubule; nucleus; azurophil granule lumen; cytoskeleton; cytosol; extracellular region; cilium; sperm flagellum
Genetic constraint (gnomAD): Loss-of-function variants: 7 observed, 34.91 expected, observed/expected ratio (o/e) 0.2, 90% interval 0.11 to 0.38. The synonymous counts are far from expectation, so gnomAD's model fits this gene poorly and the ratio says little. Missense variants: 178 observed, 630.54 expected, observed/expected ratio (o/e) 0.28, 90% interval 0.25 to 0.32. Synonymous variants: 390 observed, 260.5 expected, observed/expected ratio (o/e) 1.5, 90% interval 1.38 to 1.63.
Gene-disease validity (ClinGen):
ClinGen rates the evidence that TUBB4B causes each of these diseases.
TUBB4B-related ciliopathy (autosomal dominant): Definitive. Any ciliopathy in which the cause of the disease is a variant in the TUBB4B gene.
Homologues: Orthologues: chimpanzee TUBB4B (100% identical), dog TUBB4B (100% identical), guinea pig TUBB4B (100% identical), mouse Tubb4b (100% identical), rat Tubb4b (100% identical), pig TUBB4B (99% identical), tropical clawed frog tubb4b (99% identical), zebrafish tubb2b (98% identical), Caenorhabditis elegans tbb-4 (94% identical), Drosophila melanogaster betaTub56D (93% identical). Paralogues in human: TUBB4A (98% identical), TUBB (97% identical), TUBB2B (97% identical), TUBB2A (96% identical), TUBB3 (93% identical), TUBB6 (91% identical), TUBB8 (91% identical), TUBB8B (89% identical), TUBB1 (79% identical), TUBA1B (44% identical), TUBA1A (44% identical), TUBA1C (43% identical), and 11 more.
Diseases named in the same sentence as TUBB4B in open-access papers:
TUBB4B is named in the same sentence as 54 diseases in open-access papers, as found by Europe PMC text mining. Sharing a sentence is not in itself a finding about the gene and the disease. The quoted sentences say what the papers report.
hearing loss (4 papers, 2024 to 2025). "Genetic reinvestigation of seven additional unsolved USH patients from our database excluded variants at codons Arg390/Arg391 in these subjects, hereby underpinning that variants in TUBB4B are an ultra-rare cause of combined retinal disease and hearing loss." (PMID 38719929, 2024).
colon cancer (3 papers, 2017 to 2023). "Our studies show that as a result of TUBB4B protein decrease, which causes microtubule decomposition, the interaction between vimentin and microtubules is augmented in the invasive colon cancer cells." (PMID 31375012, 2019). "Further, we assessed the posttranslational modifications of TUBB4B in colon cancer cells undergoing EMT." (PMID 31375012, 2019). "We also focused here on the mechanism of how TUBB4B downregulation affects colon cancer cells to become more invasive." (PMID 31375012, 2019). "Accordingly, we observed a significantly lower level of TUBB4B protein in the LoVo cell line isolated from a patient diagnosed with an invasive stage of colon cancer (grade 3)." (PMID 31375012, 2019). "In the present study, we examined the role of tubulin-β4 (TUBB4B) downregulation that occurs during EMT in colon cancer cells, in the modulation of the function of microtubules." (PMID 31375012, 2019). "Based on this reasoning, we posit that modulation of beta-subunits composition by increasing of TUBB4B in colon cancer cells undergoing EMT can affect microtubule colocalization with vimentin." (PMID 31375012, 2019). "Furthermore, it has been observed that, in colon cancer cells, TUBB4B influences cell polarity and controls focal adhesions." (PMID 37511023, 2023). "Our studies suggest that the protein level of TUBB4B could be used as a marker for detection of the preinvasive stages of the colon cancer cells." (PMID 31375012, 2019). "We also concluded that chemotherapy enriched to increase TUBB4B level and/or to stabilize microtubule polymerization might more effectively prevent metastasis in colon cancer development." (PMID 31375012, 2019). "Further, we examined TUBB4B expression in LoVo cells isolated from invasive stages of colon cancer." (PMID 31375012, 2019). "Our observation suggests for the first time that the protein level of TUBB4B could be used as a marker for detection of the colon cancer cells that are in the early stage of invasiveness." (PMID 31375012, 2019). "Thus, we propose that modulation of the TUBB4B protein is critical for vimentin-microtubules interaction in invasive colon cancer cells." (PMID 31375012, 2019). "Hence, we suggest that regulation of the TUBB4B subunit may become a new target to inhibit the invasion of colon cancer, and perhaps other cancers where TUBB4B is downregulated during tumor progression to the metastatic stages." (PMID 31375012, 2019). "The data presented in these studies demonstrate for the first time that downregulation of TUBB4B and upregulation of TUBB3 observed during EMT is crucial for establishing the mesenchymal character of colon cancer cells." (PMID 31375012, 2019). "Therefore, we focused on the role of TUBB4B downregulation and TUBB3 modulation in microtubule polymerization during EMT in colon cancer progression." (PMID 31375012, 2019). "Surprisingly, our studies revealed that stimulation by TGF-β1 did not induce any changes in the level of TUBB4B phosphorylation or glycosylation in both colon cancer cell lines HT-29 and LS180 studied." (PMID 31375012, 2019).
Leber congenital amaurosis (3 papers, 2024 to 2025). Leber congenital amaurosis (LCA) is a retinal dystrophy defined by blindness and responses to electrophysiological stimulation (Ganzfeld electroretinogram (ERG)) below threshold, associated with severe visual impairment within the first year of life. "TUBB4B was reported to harbor variants that cause Leber congenital amaurosis, an eye disease, with early-onset deafness." (PMID 40650235, 2025). "In cell cycle (CD−M4), Tubb4b was associated with Leber congenital amaurosis, Dnmt1 with DNMT1 methylopathy, and Diaph3 with auditory neuropathy spectrum disorder." (PMID 39684410, 2024). "A rare AD ciliopathy is Leber congenital amaurosis with early-onset deafness (LCAEOD), caused by pathogenic variants in the TUBB4B gene." (PMID 40725402, 2025).
primary ciliary dyskinesia (3 papers, 2024 to 2025). A rare, genetically heterogeneous, primarily respiratory disorder characterized by chronic upper and lower respiratory tract disease. "Based on a cohort of 12 patients with primary ciliary dyskinesia, as well as mouse mutants, we identified and characterized variants in the TUBB4B isotype that specifically perturbed centriole and cilium biogenesis." (PMID 38662826, 2024). "Of note, some pathogenic variants of TUBB4B are associated with a distinct phenotype, primary ciliary dyskinesia (PCD), a disorder mainly affecting the respiratory system." (PMID 40725402, 2025).
ciliopathy (2 papers, 2024 to 2025). A genetic disorder of the cellular cilia or the cilia anchoring structures, the basal bodies, or of ciliary function. "In conclusion, our study provides detailed mechanistic insights into how TUBB4B variants cause a spectrum of ciliopathic diseases that spans both sensory and motile ciliopathies." (PMID 38662826, 2024). "TUBB4B-associated disease is, therefore, a ciliopathy, which primarily affects the ear, the retina and the respiratory system, but it might affect additional systems as well; the associated retinal phenotype can appear from birth to late adulthood, and present as LCA, RP or CRD." (PMID 40725402, 2025). "Overall, these results support distinct dominant-negative modes of action of TUBB4B mutations in each ciliopathy subtype." (PMID 38662826, 2024).
colorectal cancer (2 papers, 2017 to 2023). A primary or metastatic malignant neoplasm that affects the colon or rectum. "It has been shown that the downregulation of TUBB4B is crucial for the initiation of epithelial–mesenchymal transition (EMT), which is necessary for metastasis, although TUBB4B expression is upregulated in metastatic colorectal cancer lesions identified in sentinel lymph nodes." (PMID 37511023, 2023).
communicating hydrocephalus (2 papers, 2024). An abnormal accumulation of cerebrospinal fluid within the ventricles of the brain that occurs as a consequence of impaired cerebrospinal fluid reabsorption by the arachnoid granulations. "When developing the patient-relevant, precise disease model using ABE-Umax, we observed that the Q11R mutation in the fish tubb4b gene caused body curvature, hydrocephalus, and heart edema in all injected embryos." (PMID 38965236, 2024). "Given that 75% of the PCD-only cohort of TUBB4B patients also had hydrocephaly, we expected to see defects in the multiciliated ependymal cells lining the ventricles." (PMID 38662826, 2024). "However, although Tubb4b-/- mice exhibited pronounced and progressive dilatations of the ventricles neonatally without obstruction of aqueducts that suggested communicating hydrocephalus, motile cilia on ependymal cells exhibited grossly normal lengths and densities." (PMID 38662826, 2024).
Leber congenital amaurosis with early-onset deafness (2 papers, 2025). "Several of these genes are implicated in systemic disorders that can feature retinal involvement, including KIF11 (microcephaly–lymphedema–chorioretinal dysplasia), COL11A1 (Stickler syndrome), PHYH (Refsum disease), and TUBB4B (Leber congenital amaurosis with early-onset deafness)." (PMID 40923693, 2025).
melanoma (2 papers, 2023 to 2025). A malignant, usually aggressive tumor composed of atypical, neoplastic melanocytes. "TUBB, TUBB1, TUBB2A, TUBB4A and TUBB4B belong to the tubulin family, and gene expression analyses showed a higher expression of all these tubulins in melanoma compared to normal skin." (PMID 37291228, 2023).
oral cancer (2 papers, 2021 to 2024). "Studies have shown that TUBB4B plays a role in the maintenance of cancer stem cells (CSCs) in oral cancer." (PMID 38891892, 2024). "We also observed surface co-localization of TUBB4B and Ephrin-B1 in different oral cancer cell lines." (PMID 35004310, 2021). "Our immunofluorescence analysis and FACS analysis confirmed the enrichment of cells expressing TUBB4B or Ephrin-B1 on the cell surface in sphere cultures of oral cancer cell lines." (PMID 35004310, 2021). "Similar experimental analysis with the tissue sections of oral squamous cell carcinoma (OSCC) corroborated with the results obtained from the xenograft sections further confirming the role of TUBB4B in constituting a CSC niche in oral cancer." (PMID 35004310, 2021). "When the clinical data suggested a functional interaction between TUBB4B and Ephrin-B1 regulating survival, we sought to investigate how they cooperate to regulate CSCs in oral cancer." (PMID 35004310, 2021). "Here, we provide evidence of TUBB4B-mediated regulation of Ephrin-B1 localization that supports the CSC niche in oral cancer." (PMID 35004310, 2021). "To test out cooperation between TUBB4B and Ephrin-B1 in oral cancer, we initially checked whether the expressions of these proteins are involved in the progression of oral cancer using data retrieved from the TCGA repository." (PMID 35004310, 2021). "The present study aims to investigate the role of TUBB4B in the maintenance of CSCs in oral cancer." (PMID 35004310, 2021). "As our study demonstrates relevance of TUBB4B in Oral cancer stem cell niche, we believe targeting TUBB4B using specific small molecule inhibitors could be a potential aid in clearing the CSC population by creating an imbalance in the CSC niche." (PMID 35004310, 2021). "Further, we used the IPTG inducible lentiviral TUBB4B shRNA constructs in HSC-3 cells expressing ALDH1A1-DsRed2, a confirmed reporter for CSCs in oral cancer." (PMID 35004310, 2021). "Even though the expression of TUBB4B was evaluated in some studies, its role in the regulation of oral cancer CSCs is not well explored in oral cancer." (PMID 35004310, 2021).
colitis (1 paper, 2025). Inflammation of the colon. "Sera from four patients who developed both skin toxicity and colitis/diarrhea also showed increased autoantibodies to tubulins (TUBB2A, TUBB4A, TUBB, TUBB4B) on treatment." (PMID 40449958, 2025).
COVID-19 (1 paper, 2024). A disease caused by infection with severe acute respiratory syndrome coronavirus 2. "Our comprehensive analysis revealed that four common genes, B4GALNT2, MTX1, POLR2J, and TUBB4B are differentially expressed in patients with both COVID-19 and diabetic peripheral neuropathy." (PMID 38957825, 2024).
escherichia coli infection (1 paper, 2024). Infection with the organism Escherichia Coli. "Meanwhile, the TUBB4B gene activates the pathogenic Escherichia coli infection WP2272 and the Parkin-Ubiquitin Proteasomal System pathway WP2359." (PMID 38957825, 2024).
glioma (1 paper, 2024). A benign or malignant brain and spinal cord tumor that arises from glial cells (astrocytes, oligodendrocytes, ependymal cells). "Moreover, the GSCs encompass not only encompasses known glioma genes, but also novel targets, such as HMGN2, TUBB4B, and ARL6IP1, that warrant further investigation." (PMID 39355251, 2024).
hepatocellular carcinoma (1 paper, 2025). A malignant tumor that arises from hepatocytes. "Recently, tubulin beta 4B class IVb (TUBB4B, also known as TUBB2C) was shown to promote non-alcoholic fatty liver disease-associated hepatocellular carcinoma (NAFLD-HCC)." (PMID 39962586, 2025).
Huntington disease (1 paper, 2024). Huntington disease (HD) is a rare neurodegenerative disorder of the central nervous system characterized by unwanted choreatic movements, behavioral and psychiatric disturbances and dementia. "Both TUBB4B POLR2J genes worked on Huntington's disease and RNA polymerase." (PMID 38957825, 2024).
inherited retinal dystrophy (1 paper, 2024). An instance of retinal degeneration that is caused by an inherited modification of the individual's genome. "Our purpose was to elucidate the genotype and ophthalmological and audiological phenotype in TUBB4B-associated inherited retinal dystrophy (IRD) and sensorineural hearing loss (SNHL), and to model the effects of all possible amino acid substitutions at the hotspot codons Arg390 and Arg391." (PMID 38719929, 2024).
lung carcinoma (1 paper, 2023). "In conclusion, this study identifies IFI30, RNH1 and CLEC3B, VCAN, IGFBP2, C2, TUBB4B as the proteins secreted by lung carcinoma cells and monocytes respectively as a result of their mutual interaction." (PMID 37784035, 2023). "Thus the finding provides evidence that lung cancer cells modulate monocytes to release TUBB4B which in turn promotes cancer metastasis." (PMID 37784035, 2023). "In this study, we have demonstrated that the lung cancer cell-monocyte cross-talk modulates the secretion of IFI30, RNH1, CLEC3B, VCAN, IGFBP2, C2 and TUBB4B favoring tumor growth and metastasis." (PMID 37784035, 2023).
oral squamous cell carcinoma (1 paper, 2021). "Based on that result, we investigated whether TUBB4B regulates CSCs using in vitro CSC reporter system, pluripotency markers, in vitro serial dilution spheroid formation assay, in vivo serial dilution xenograft assay, and immunohistochemical analysis of oral squamous cell carcinoma (OSCC) samples." (PMID 35004310, 2021).
ovarian carcinoma (1 paper, 2021). A malignant neoplasm originating from the surface ovarian epithelium. "A recent study proposed TUBB4B as a potential marker in Ovarian Cancer, wherein they report an increased level of TUBB4B in ovarian cancer patient plasma samples in comparison to healthy and benign non-cancerous samples." (PMID 35004310, 2021).
Parkinson disease (1 paper, 2023). A progressive degenerative disorder of the central nervous system characterized by loss of dopamine producing neurons in the substantia nigra and the presence of Lewy bodies in the substantia nigra and locus coeruleus. "Moreover, Parkinson’s disease (NDUFA9, TUBB4B, etc.; p-value = 4.94E-21), Prion disease (UQCR10, SDHA, etc.; p-value = 4.82E-17) and Pathways of neurodegeneration - multiple diseases (UBA52, etc.; p-value = 6.44E-16) were linked to the low abundant proteins in HF." (PMID 36891514, 2023).
retinal degeneration (1 paper, 2024). Degeneration of the retina. "Pathogenic variants in TUBB4B have been associated with an autosomal dominantly inherited form of early retinal degeneration and hearing loss." (PMID 38719929, 2024).
thyroid cancer (1 paper, 2023). "TUBB4B, another member of the TUBA1A family, is a prognostic marker in endometrial, liver, and thyroid cancers." (PMID 37511023, 2023).